PDC (phosducin)
Diseases named in the same sentence as PDC in open-access papers (continued):
Sharing a sentence is not in itself a finding about the gene and the disease.
Autoimmunity (11 papers, 2008 to 2024). The occurrence of an immune reaction against the organism's own cells or tissues. "We also highlight the current understanding of pDC involvement in autoimmunity and alloreactivity, and opportunities for pDC‐targeting therapies in these diseases." (PMID 32489664, 2020). "In this review, we will discuss the relative contribution of innate and adaptive pDC functions in modulating T cell responses, particularly during the development of autoimmunity." (PMID 23508732, 2013). "PPT1 may be a great drug target to treat IFN-I-mediated autoimmunity, because its inhibition may simultaneously enhance cDC1-dependent cross-priming and suppress pDC-dependent IFN-I production." (PMID 38169466, 2024). "Finally, we also highlight the current understanding of pDC involvement in autoimmunity and alloreactivity, and opportunities for pDC‐targeting therapies in these diseases." (PMID 32489664, 2020). "The role of pDC lifespan and state of autoimmunity in these patients should be examined further." (PMID 31811114, 2019). "Circumvention of Treg-mediated suppression and activation of autoreactive T cells by pDC might precise the involvement of pDC in autoimmunity." (PMID 22952871, 2012). "Nonetheless, the importance of pDC activation at early disease stages is consistent with studies suggesting that pDC depletion or IFNAR blockade more efficiently reduce systemic autoimmunity when applied before a critical threshold of immune activation is exceeded." (PMID 30199535, 2018). "As pDCs are involved in inflammatory responses which may be detrimental to the neonatal brain and IFN-I contributes to increasing the risks of autoimmunity, it is biologically plausible that the slow onset of pDC activation and IFN-I responses has beneficial effects." (PMID 24376875, 2013). "Although pDC-mediated activation of bystander lymphocytes following rotavirus exposure is conserved between autoimmune and non-autoimmune mouse models, the presence of autoreactive T cells in adult NOD mice is likely to skew the outcome of this response towards increased autoimmunity." (PMID 24676425, 2014).
breast carcinoma (11 papers, 2018 to 2024). "Although pDC infiltration is associated with poor outcomes in human breast cancer, pDC can induce tumor regression through type I IFN-mediated mechanism following intratumoral injection of TLR7 ligand in orthotopic murine mammary tumor model." (PMID 36244976, 2022). "PDC infiltration into the tumor bed has been associated with poor prognosis in breast cancer and pDC-driven expansion of regulatory T cells has been implicated in this immunosuppression." (PMID 31440253, 2019). "Subsequently, tumor digests of breast cancer samples with solid pDC infiltration and whole blood samples of healthy donors were stimulated with a TLR7 agonist (RO7117419) for 24 hrs." (PMID 39575246, 2024). "Recent studies and the results of Section 2.1 in this paper showed that pDC infiltration has a stronger correlation with survival in breast cancer patients than cDC infiltration." (PMID 36835467, 2023). "Infiltration by pDC of breast tumor correlates with dissemination and relapse, suggesting pDC contributes to the progression of breast cancer." (PMID 34109210, 2021). "The pDC recruitment has been documented in human primary breast cancer, and the corresponding metastatic sentinel lymph nodes (SLNs) in response to CXCL12/SDF1, including only a minor fraction with a mature phenotype." (PMID 32054102, 2020). "Using the TCGA and METABRIC cohorts of breast cancer patients, we found that transcriptionally defined levels of cDC and pDC infiltration were elevated in TNBC compared to other subtypes of breast cancer." (PMID 33198125, 2020). "To validate if this is also true in the lactate-rich tumor microenvironment in human patients, we looked at breast cancer, as intra-tumoral pDC-dysfunction is well-documented in these patients." (PMID 31440253, 2019). "In the present study we explored if this major oncometabolite also regulated intra-tumor pDC function in breast cancer." (PMID 31440253, 2019). "On the contrary, depletion of pDC inhibits progression and bone metastasis of the breast cancer." (PMID 34109210, 2021). "Furthermore, a high frequency of circulating pDCs correlates with prolonged overall survival in breast cancer and pancreatic cancer patients, while a higher MDSC/pDC ratio has been associated with poor survival in NSCLC." (PMID 32054102, 2020). "However, the prognostic role of the pDC in breast cancer (BRCA) was controversial." (PMID 33869191, 2021).
influenza (10 papers, 2009 to 2024). An acute viral infection of the respiratory tract, occurring in isolated cases, in epidemics, or in pandemics; it is caused by serologically different strains of viruses (influenzaviruses) designated A, B, and C, has a 3-day incubation period, and usually lasts for 3 to 10 days. "Such toxicity of type I IFNs is likely exerted through pDC-mediated reactions since pDCs are major producers of type I IFNs and are required for whole-virion inactivated influenza vaccine leukocyte-related toxicity in mice." (PMID 38932312, 2024). "In contrast to HIV, influenza is rapidly endocytosed by pDC and triggers a strong NF- κB activation, secretion of inflammatory cytokines, and maturation of pDC." (PMID 27082754, 2016). "The public mouse expression data used in this study uncovered a set of highly expressed pDC genes for CpG in DNA and a different, but strongly overlapping, set from influenza." (PMID 19536338, 2009). "Murine studies have indicated that pDC provide a major contribution to IFN type I responses during influenza." (PMID 21994580, 2009). "Therefore in the case of pregnancy, impaired pDC responses may not be enough alone to explain the susceptibility seen in pregnant women to influenza." (PMID 25831059, 2015). "While depletion of pDC, in the lungs of mice, affected IFNα levels following influenza, this was not the case with RSV, suggesting that pDCs play a less important role in type 1 IFN production during RSV infection than in influenza." (PMID 29552008, 2018). "Also, Influenza causes an acute infection that is rapidly cleared and the chronicity of LCMV clone 13 may not be sufficient and may rather suppress pDC functions." (PMID 34497606, 2021).
asthma (9 papers, 2011 to 2024). "The function of pDC also appears to be abnormal in asthma, with reports demonstrating that pDC from allergic asthmatics are less able to synthesise IFNα in response to influenza A or TLR9 activation than pDC from healthy subjects." (PMID 25203745, 2014). "While the exact role viruses play in the overall development of asthma and atopic disease remains controversial, the data are compounding to suggest that resident lung cDC and pDC play a critical role in this process." (PMID 23118777, 2012). "This is consistent with our finding that pDC depletion produced significantly lower IL-6 and IFN-α, and somewhat lower TNF-α, consistent with the notion that pDC function might be impaired in asthma." (PMID 29118754, 2017). "Together it appears that in asthma the dysregulated immunity to respiratory viral infections is mediated not only by structural cells in the lung but also by circulating leukocytes, possibly pDC." (PMID 22125636, 2011). "This could help leverage pDC functions for better clinical management of asthma exacerbations." (PMID 39530090, 2024). "The recruitment of pDC may be part of the anti-inflammatory response in asthma." (PMID 24330650, 2013). "Thus, for a proper response to omalizumab, pDC may be central in improving asthma symptoms." (PMID 38006387, 2023). "Indeed, pDC function may play a significant role in the pathogenesis of asthma." (PMID 34299892, 2021). "PDC depletion in BALB/c mice also resulted in enhanced airway inflammation and eosinophilia in asthma models, whereas adoptive transfer of pDCs suppressed inflammation and the Th2 response." (PMID 22072972, 2011).
atherosclerosis (6 papers, 2014 to 2022). A disease characterized by the build-up of fatty material and calcium deposition in the arterial wall resulting in partial or complete occlusion of the arterial lumen. "The authors confirmed the scarce presence and anatomical location of pDCs in the intimal space and adventitia, as previously demonstrated; moreover, total aortic pDC numbers increased with atherosclerosis progression." (PMID 28243244, 2017). "In order to scrutinize the role of pDCs in atherosclerosis we employed a specific pDC-depleting antibody." (PMID 24818041, 2014). "Cramp-self-DNA complexes that could form in atherosclerotic lesions may thus trigger pDC activation also in atherosclerosis." (PMID 24818041, 2014). "Furthermore, pDC-specific deletion of MHCII molecules also reduced the development of atherosclerosis via defective activation of antigen specific CD4+T cells, accompanied by a marked reduction of the T cell-produced inflammatory cytokine IFN-γ and T cell migration into the lesion." (PMID 32849502, 2020). "Given that such antibody complexes that contain self-DNA as well as antimicrobial peptides can furthermore trigger pDC activation and IFN-α production, anti-dsDNA antibodies, generated as a consequence of pDC-activation, may contribute to the pathogenic insult in atherosclerosis." (PMID 24818041, 2014). "Although this indicates that one-week pDC depletion does not affect atherosclerosis in these settings, these results do not argue against a role of pDCs in early or advanced lesions." (PMID 26252890, 2015).
colitis (6 papers, 2018 to 2025). Inflammation of the colon. "Taken together, these results indicate that pDC migration is essential for the pathogenic mechanism of OXZ colitis." (PMID 34997096, 2022). "In contrast to the data shown here, pDC-depleted mice developed less severe colitis than wild type mice with lower levels of weight loss, colonic inflammation, and production of inflammatory cytokines." (PMID 31024525, 2019). "pDC depletion impaired the gut barrier function and led to severe colitis in a Citrobacter rodentium-induced colitis model." (PMID 36262975, 2022). "Arimura and co-workers propose a role of pDCs in colitis development, as pDC-ablated mice showed ameliorated symptoms upon colitis induction with DSS, decreased production of inflammatory cytokines and a lower leukocyte influx into the colonic lamina propria." (PMID 29570694, 2018). "Therefore, we studied whether pDC impairment affects colitis development in Was-deficient mice." (PMID 30410494, 2018). "Because Tcf4 haplodeficiency results in only a partial impairment of pDCs, we sought to examine the effect of a more profound pDC depletion on colitis." (PMID 30410494, 2018). "This is associated with enhanced IFNAR dependent infection-induced-colitis when LDHB expressing pDCs are transferred into infected mice, suggesting the conservation of pDC inhibition after infection may be a mechanism to avoid excessive pathology." (PMID 39920132, 2025). "While enteric viruses activate pDC production of IFN-I ex-vivo, direct in vivo evidence for pDC functions in the prevention of colitis development after infection with enteric viruses has not been demonstrated." (PMID 30410494, 2018).
malaria (6 papers, 2015 to 2022). Malaria is a serious and sometimes fatal disease caused by a parasite that commonly infects a certain type of mosquito which feeds on humans. "Circulating pDC in P. falciparum infected Fulani, an ethnic group less susceptible to symptomatic malaria, on the contrary, display a mature phenotype with upregulated CD86 and HLA-DR expression and strong TLR9 responsiveness." (PMID 28572564, 2017). "This reinforces the need to study pDC function during malaria to understand whether a loss of pDC numbers in the periphery is associated with a concomitant loss of function." (PMID 30886619, 2019). "In conclusion, our analysis of the dynamic behavior of pDC in vivo by IVM directly in the BM of mice undergoing severe murine malaria, reinforce a model in which pDC sensing of their ligands in vivo is a highly coordinated and orchestrated process." (PMID 36278864, 2022). "Much less is known about the role of pDC in human malaria, mainly due to limitations intrinsic to human studies and restrictions to peripheral blood." (PMID 28572564, 2017). "Murine models of malaria show differing pDC responses, depending on the mouse strain and parasite species." (PMID 28572564, 2017). "To gain insights into human pDC function in malaria, we took advantage of the CHMI, which allowed longitudinal assessment of pDC function in malaira naive volunteers." (PMID 28572564, 2017). "Altogether our findings describe a novel mechanism of pDC activation in vivo and precise stepwise cell/cell interactions taking place during severe malaria that contribute to immune cell activation and inflammation, and subsequent disease outcomes." (PMID 27792766, 2016). "In the human malaria parasite Plasmodium falciparum, the single PDC is located exclusively in the apicoplast." (PMID 25387830, 2015). "The relevance of pDC activation in murine malaria is debated." (PMID 28572564, 2017). "The role of human pDC in malaria remains poorly characterised." (PMID 28572564, 2017). "Plasmodium PDC is essential for parasite survival in the mosquito vector and for late liver stage development in the human host, suggesting its suitability as a target for intervention strategies against malaria." (PMID 25387830, 2015). "Using a mouse model of severe malaria, we have previously established that upon priming by CD169+ macrophages (MPs), pDC initiates type I IFN-I secretion in the bone marrow (BM) of infected mice via cell-intrinsic TLR7 sensing and cell-extrinsic STING sensing." (PMID 36278864, 2022). "The lack of evident pDC activation in both early infection and malaria suggests little response of circulating pDC to infection." (PMID 28572564, 2017). "Whether pDC activation is desirable or detrimental in human malaria is still not clear." (PMID 28572564, 2017).
Arthritis (5 papers, 2018 to 2025). Inflammation of a joint. "It is already known that PDC-deficient mice show exacerbation of inflammatory and arthritis symptoms." (PMID 38068720, 2023). "Synovial pDCs can produce robust IFN-α, and persistent arthritis has been induced by intra-articular transfer of IFN-I-producing DCs; conversely, in other models, pDC deficiency exacerbates arthritis, and disease activity improves with pDC mobilization/activation via TLR7 agonists." (PMID 41301504, 2025). "Conversely, enhancing PDC recruitment and activation to arthritic joints by topical application of the Toll-like receptor 7 (TLR-7) agonist imiquimod significantly ameliorated arthritis." (PMID 38068720, 2023). "Furthermore, the transfer of pDC from SuperMApo-treated CIA mice into untreated CIA mice did not modify the course of arthritis." (PMID 30542342, 2018). "Resolution of arthritis was conserved in absence of pDC together with a preserved immunomodulation to collagen auto-antigen, demonstrating the dispensable role of pDC." (PMID 30542342, 2018).
breast tumor (5 papers, 2019 to 2021). "It has been documented that, through TRAIL and Granzyme B, the activated pDC can kill breast tumor cells." (PMID 33869191, 2021). "We analyzed pDC frequency in peripheral blood and tumors by comparing HIS-NOG-EXL with HIS-NOG mice bearing three different ovarian and breast tumors." (PMID 33013879, 2020).
glioma (5 papers, 2019 to 2025). A benign or malignant brain and spinal cord tumor that arises from glial cells (astrocytes, oligodendrocytes, ependymal cells). "Therefore, elevated CENP-A expression may induce Th2 cell infiltration and pDC deficiency in the tumor microenvironment, which contributes to immunotherapy resistance and poor treatment response in glioma." (PMID 36105094, 2022). "Diffuse low-grade glioma with a better outcome showed elevated pDC level." (PMID 36105094, 2022). "pDC dysfunction induced by impaired IFN-α secretion and upregulation of immune checkpoint mediators was often observed in tumors, including gliomas." (PMID 35372355, 2022).
multiple myeloma (5 papers, 2019 to 2021). "While pDC can normally be activated to cause apoptosis of myeloma cells, pDC-myeloma binding via E-cadherin can convert pDC into tumor promoting cells." (PMID 33634031, 2020). "More recent study from this group has identified a novel TLR-9 agonist that inhibited pDC-induced myeloma cell growth and triggered apoptosis, restoring the T cell stimulation." (PMID 34442012, 2021). "The strong interaction of pDC and multiple myeloma (MM) cells induce the secretion of IL-3, which stimulates both pDC survival and MM cell survival and proliferation." (PMID 33418996, 2021). "Conversely, in multiple myeloma, downregulation of IFN-I production by pDC is caused by cell-to-cell contact between pDC and tumor cells." (PMID 30979057, 2019). "Importantly, pDC depletion induced tumor regression in a myeloma mouse model providing pDCs as new targets for improving MM outcomes." (PMID 34442012, 2021). "Additionally, they reported that SL-401 induces pDC apoptosis, which resulted in overcoming treatment resistance in multiple myeloma." (PMID 30621282, 2019). "Outcomes in other hematologic malignancies, such as multiple myeloma and chronic myelomonocytic leukemia, are still in early clinical trials, and these studies are providing a better understanding of the bone marrow microenvironment and the role of pDC in tumor progression and treatment resistance." (PMID 30621282, 2019).
ovarian carcinoma (5 papers, 2019 to 2024). A malignant neoplasm originating from the surface ovarian epithelium. "cDC1, cDC2, and pDC are found in ovarian cancer, with a lower rate of both cDC and pDC in the peripheral blood compared with healthy control." (PMID 33584699, 2020). "According to Lee's research, we speculate that the high expression of PDK1 in ovarian cancer results in the inhibition of PDC in tumor cells, which drives the switch to fatty acid oxidation, promotes the metastasis of cancer cells and accelerates the adverse prognosis of ovarian cancer." (PMID 33403023, 2021).
Sepsis (5 papers, 2018 to 2025). Sepsis is defined as life-threatening organ dysfunction caused by a dysregulated host response to infection. "Collectively, these results suggested that IL-3 enhances antiviral immune responses during sepsis by improving pDC-mediated T cell immunity." (PMID 36911737, 2023). "We next projected the cDC2 gene modules onto pDC and cDC1 and found that the red module was also highly expressed in cDC1 B and pDC B, as well as in sepsis." (PMID 37781404, 2023). "As few studies have investigated pDC during endotoxemia and sepsis, there is a need to revisit the role of pDCs during endotoxemia and sepsis." (PMID 29740436, 2018).